MET (MET proto-oncogene, receptor tyrosine kinase)
Diseases named in the same sentence as MET in open-access papers (continued):
Sharing a sentence is not in itself a finding about the gene and the disease.
tumor (continued). "In routine studies, SNP 6.0 and FISH are the standard methods to evaluate the MET copy number of cancer cell lines in vitro and tumor samples in vivo, respectively." (PMID 26765781, 2016). "In contrast, tumorgrafts 200 and 201 were derived from metastatic TNBCs, have 4–5 copies of MET, and have a complete tumor growth inhibition to MET monotherapy with MGCD265." (PMID 27655711, 2016). "Tumors treated with vehicle, or the MET inhibitor alone, reached the experimental endpoint (tumor volume = 1,600 mm3) within 18 or 32 days, respectively." (PMID 27138567, 2016). "In another study, 21.2% of formalin-fixed, paraffin-embedded (FFPE) primary tumor tissues exhibited MET amplification defined as copy number >4 by qPCR." (PMID 27013592, 2016). "Taken together, we show for the first time that transcriptional upregulation of MET is a key molecular event associated with CRC invasion and tumor budding." (PMID 27793046, 2016). "NKTCL cells were found to produce HGF and activate the HGF/c-MET signaling pathway for the tumor cell proliferation in an autocrine manner." (PMID 27923392, 2016). "At baseline, increased phosphorylation of c-MET was observed in normal tissue compared with tumor tissue." (PMID 26742633, 2016). "At day 26, the BpAb still showed significant tumor growth inhibition in comparison to the IgG1 control (P equals to 0.003), confirming the superior biological activity of the anti-MET BpAb compared to the parental mAbs." (PMID 27546726, 2016). "MET overexpression has been shown to induce tumor growth and angiogenesis, thus facilitating tumor metastasis." (PMID 27058528, 2016). "Because MET is involved in the regulation of tumor cell survival and metastasis, a better understanding of individual patient sensitivities to MET inhibitors can help guide clinical trial design." (PMID 27013592, 2016). "HGF/MET signaling pathway activation can occur via MET gene amplification, overexpression, mutations or paracrine and autocrine activation of MET by HGF, all of which have been observed in multiple human tumor types." (PMID 27013592, 2016). "To support the results of our in vitro experiments, we examined MET gene and protein expression in situ in budding tumor cells at the invasive front using CRC clinical tissues." (PMID 27793046, 2016). "c-MET signaling plays a critical role in tumor progression, invasion, and metastasis, and we have recently shown it to be associated with poor prognosis in locally advanced HNSCC patients treated with chemoradiation." (PMID 26880935, 2016). "The results of the NanoPro1000 analysis showed increased fluctuations in c-MET phosphorylation in normal compared with tumor tissue in response to ischemia." (PMID 26742633, 2016). "In preclinical studies, biomarker analysis has shown that MET-amplified and MET-overexpressing tumor xenograft models are highly responsive to volitinib as a single agent or in combination with other therapies." (PMID 27013592, 2016). "In both cohorts, MET amplification was correlated with high cell proliferation or high tumour grade." (PMID 27175600, 2016). "In samples analyzed using our tumor genotyping panel, MET gene copy number gain was seen in two of 27 samples (7 %)." (PMID 27821131, 2016). "The MET-positive tumors were defined as such when at least 25% of tumor cells demonstrated membrane staining at any intensity using the MET4 monoclonal antibody and the verified MET immunohistochemistry pharmDx kit (Dako North America, Carpinteria, CA, USA)." (PMID 27013592, 2016). "Cabozantinib has inhibited tumor growth in p-MET-positive and p-MET-negative HCC by decreasing angiogenesis, inhibiting proliferation, and promoting apoptosis." (PMID 27881963, 2016). "According to this study, MET-positivity by IHC in tumor tissues is considered a predictive marker for efficacy of anti-HGF antibody in metastatic GC patients." (PMID 26716644, 2016).
tumor (continued). "To further investigate MET as a mechanism of resistance to rociletinib, we identified an expanded cohort of 16 patients with T790M-mutant tumours participating in rociletinib trials who had MET copy-number gain detected in pre-treatment biopsies or plasma." (PMID 27283993, 2016). "A moderate to intense cytoplasmic staining of tumor cells (H score = 2 to 3) with EGFR and MET Abs, and a moderate to intense nuclear staining of tumor cells (H score = 2 to 3) with CDK6 Abs were considered to define IHC positivity." (PMID 27329726, 2016). "Among a group of biologically important targets for cancer intervention, MET is a receptor tyrosine kinase (RTK) that has low activity in normal tissues but is dysregulated in many tumor types." (PMID 28536405, 2015). "In tumor biopsies, MET was found to be overexpressed in selected types of solid tumors, and HGF was widely detected in the intratumoral spaces of solid tumors." (PMID 28536405, 2015). "The current study suggests that higher EGFR/MET ratios correlate with a tumor's addiction to the EGFR pathway." (PMID 26439803, 2015). "Our study, then, uses xenograft mouse models plus human and mouse arrays to provide preliminary, yet important, information about the tumor/host interaction in response to MET inhibitors." (PMID 26381735, 2015). "Our data revealed that upregulation of sf-RON in MET-addicted tumor cells attenuated PF-induced suppression of cell proliferation and migration." (PMID 26528757, 2015). "We compared staining intensities of the MET specific antibody clone SP44 in formalin fixed paraffin embedded tissue versus HOPE-fixed tumor samples." (PMID 26215852, 2015). "One molecule that has been shown to be involved in resistance to EGFR inhibitors in different tumor types is MET, the receptor tyrosine-kinase for hepatocyte growth factor (HGF)." (PMID 26319934, 2015). "Activation of c-MET promotes cell proliferation, survival, motility, and invasion, all features of tumour growth and progression (reviewed in6)." (PMID 26138303, 2015). "The prime interest of the current study was to evaluate in vitro as well as in an orthotopic liver tumor model the potential of two MET small molecules inhibitors, SU11274 and PHA665752 to interfere with tumor-associated angiogenesis." (PMID 26413215, 2015). "Several resistance mechanisms including upregulation of proangiogenic signaling pathways, increased AXL and MET expression, inadequate target inhibition, and resistance mediated by the tumor microenvironment or by the action of microRNAs have been reported." (PMID 28326274, 2015). "Tivantinib (ARQ 197) is a selective, orally available, small-molecule MET inhibitor that preferentially inhibits growth of cells, and induces apoptosis in human tumor cell lines expressing MET." (PMID 28943630, 2015). "Increased mesenchymal–epithelial transition factor gene (c-MET) expression in several human malignancies is related to increased tumour progression." (PMID 26459369, 2015). "For example, the restoration of miR-34a-5p, a tumor suppressive miRNA that simultaneously downregulates the expressions of MET, PDGFRA and CDK6, can possibly outperform any single targeted agents tailored to those targets." (PMID 26439688, 2015). "Cabozantinib (CBZ) is a receptor tyrosine kinase (RTK) inhibitor with potent activity against multiple RTKs, including VEGFR-2 and MET, that mediate tumour survival, metastasis and angiogenesis and are also expressed by a number of cell types in bone." (PMID 26279137, 2015). "In our current analyses, AUY922 significantly reduced the invasive and migratory capabilities of both tumor cells with MET or AXL activation." (PMID 25780909, 2015).
tumor (continued). "In our study, MET phosphorylation at Y1234/1235 was detected in 14 % of the investigated NSCLC tumor samples, phosphorylation of Y1349 was observed in 17.7 %." (PMID 26215852, 2015). "To explore this, we combined the use of human and mouse microarrays to study gene expression changes in tumor cells and host cells in response to MET inhibitors." (PMID 26381735, 2015). "Of 209 tumor tissues, evaluated by IHC for the expression of MET and positive for phosphorylation at Y1234/1235, 20 (9.6 %) were classified as ADC, 9 (4.3 %) were categorized as SCC and 1 (0.5 %) as LCC." (PMID 26215852, 2015). "In vivo expression of decoy c-MET inhibits tumor cell proliferation and survival in a variety of human xenografts, impairs tumor angiogenesis by preventing host vessel arborization, and suppresses or prevents the formation of spontaneous metastases." (PMID 28536400, 2015). "Two tumors had focally more than ≥15 MET gene copies/cell in ≥10% of tumor cells and one tumor had a focal MET/CEN7 ratio ≥2.0." (PMID 25844809, 2015). "Activation of the HGF/c-MET axis induces different phenotypes depending on tumor stage: inducing proliferation and angiogenesis in primary tumors, stimulating motility to form micrometastases, and regaining the proliferation phenotype to form overt metastases." (PMID 28536400, 2015). "To examine other mechanisms underlying the reduced tumor growth and change in cell morphology, we assessed the expression of EMT-related genes in MET-deficient cells." (PMID 25888626, 2015). "Because not only expression but also activation of MET is essential for tumor progression, we also analyzed the phosphorylation status of the receptor by IHC with two phosphorylation specific antibodies." (PMID 26215852, 2015). "Sections of primary tumor from patients with a rare type of BCa, called neuroendocrine (NE) BCa, show c-MET expression." (PMID 26225770, 2015). "Treated with c-MET inhibition however, c-MET positive cells had increased apoptosis, decreased proliferation and suppressed tumour growth, while c-MET reduced cells survived the inhibition treatment." (PMID 28943627, 2015). "Overexpression of c-MET has been described in many tumor types such as gastric, oesophageal or lung." (PMID 26334097, 2015). "Accordingly MET activation diminished apoptosis of tumor cells in vivo, as demonstrated by staining for cleaved PARP." (PMID 26384300, 2015). "Activated HGF/c-MET signaling is reported to play an important role in tumor stromal-interactions under hypoxia." (PMID 28536400, 2015). "It is possible that during tumor development, some transdifferentiation takes place, which is more prominently revealed after MET downregulation." (PMID 25888626, 2015). "Substantial growth inhibition of METex14del+ patient tumor derived cell lines by several MET targeting drugs strongly suggests METex14del is a potential actionable driver mutation in GI malignancies." (PMID 26375439, 2015). "Mounting studies highlighted the essential role of the HGF/c-MET axis in driving HCC tumor progression." (PMID 25607934, 2015). "MET gene copy number correlated with tumor size by trend and lymph node status (both: spearman correlation coefficient rs = 0.132; p = 0.012)." (PMID 26215852, 2015). "In conclusion, these results confirm that SAIT301 induces degradation of MET in METex14+ PDCs by down-regulating MET in Cbl-independent manners and subsequent inhibition of tumor cell growth." (PMID 26375439, 2015). "HGF secreted by stromal cells in the tumor microenvironment can activate the HGF receptor MET, initiating MAPK and PI3K signaling to confer resistance to BRAF inhibition." (PMID 25763355, 2015). "In consistence with recently published literature, this suggests that active MET signaling contributes to dissociative tumor growth, tumor progression and invasion." (PMID 25884643, 2015).
tumor (continued). "The commonly measured biomarkers are circulating HGF and MET levels, MET protein expression levels in tumor tissues, and MET gene amplification, copy number, and mutation, as well as markers related to the crosstalk of related pathways." (PMID 28536405, 2015). "It has demonstrated strong dose-dependent anti-tumour activity and dose-dependent reduction of phosphorylated MET (pMET) levels in c-MET-dependent murine tumour models." (PMID 28943627, 2015). "When comparing protein expression with their paired-control sample, ARID1A levels were lower in 42.4% of the tumor tissues whereas c-MET and PIK3CA levels were higher in 36.4% and 63.6% of the tumor tissues analyzed." (PMID 26334097, 2015). "In vivo, HGF and its receptor, the c-MET proto-oncogene product, are thought to be involved in embryogenesis, tissue reorganization, and tumor progression." (PMID 26090722, 2015). "In a randomized phase 2 study evaluating onartuzumab, a monoclonal antibody directed against MET, only 12 % of patients with TNBC had moderate to high expression of MET (IHC 2+/3+ in 50 % of stained tumor cells)." (PMID 26123926, 2015). "It has been previously shown that MET deletion in mouse neutrophils enhances tumor growth and metastasis." (PMID 26384300, 2015). "Expression of MET-T1010I in the context of mammary epithelium increases colony formation, cell migration and invasion in-vitro and tumor growth and invasion in-vivo." (PMID 25605252, 2015). "MetMab downregulates constitutively active c-MET in tumor cell lines, and is currently in phase I/II human clinical trials in comparison with erlotinib in patients with non-small-cell lung cancer." (PMID 28536400, 2015). "The MET inhibitors regulate tumor and host crosstalk, and overall impede tumor growth by inhibiting cell cycle progression." (PMID 26381735, 2015). "Regarding tumor grade, MET amplification was observed in 18% of well/moderately differentiated tumors (7 of 39) and 19.3% (11 of 57) in low differentiated tumors." (PMID 26208325, 2015). "Crizotinib targets the receptor MET, which is frequently activated in human cancers promoting tumor growth, invasion and dissemination." (PMID 25608652, 2015). "The present study showed that c-MET protein is concomitantly overexpressed in both primary tumours and in nodal metastasis which is similar other studies findings." (PMID 26459369, 2015). "To assess the impact of MET inhibition on tumor angiogenesis, we evaluated the state of blood vessels in the tumor sections by immunohistochemical staining using an antibody against the endothelial cell surface marker CD31." (PMID 26413215, 2015). "A number of novel therapeutic agents—either as therapeutic proteins or small molecules that target the HGF/MET pathway—have been tested in patients with different tumor types in clinical studies." (PMID 28536405, 2015). "The single responder did not have evidence of MET expression by IHC or clear evidence of MET amplification in her archival tumor specimen, so it is unclear if her response was due to inhibition of MET." (PMID 26123926, 2015). "MET (a receptor tyrosine kinase) is an oncogene that plays a role in tumour metastasis and motility." (PMID 25673052, 2015). "The MET inhibitors regulate tumor (human) and host (mouse) cells within the tumor via distinct molecular processes, but overall impede tumor growth by inhibiting cell cycle progression." (PMID 26381735, 2015). "Mechanistically, the transmigration of anti-tumoral Met+ neutrophils was dependent on expression of high levels of hepatocyte growth factor (HGF), the only ligand for MET, by the tumor." (PMID 26438048, 2015). "Polysomies were evident in 2.3 % of analyzed tumor samples (corresponds to 2.4 % of 209 tumor samples analyzed for MET expression)." (PMID 26215852, 2015). "Of the 5 PDC cell lines, four METex14del+ cell lines were tested for potential anti-tumor efficacy of c-MET inhibitors, crizotinib (small molecule) and SAIT301 (monoclonal antibody)." (PMID 26375439, 2015).
tumor (continued). "Overall, the interconnected and diverse functions of the HGF/c-MET axis in driving tumor growth support the role of the microenvironment milieu in directing the metastatic spread of the primary tumor." (PMID 28536400, 2015). "Activation of the MET oncogene promotes tumor growth, invasion and metastasis in several tumor types." (PMID 26319934, 2015). "For a limited number of tumor samples, MET expression was also evaluated on mRNA level and compared with MET expression evaluated by Western Blot analysis." (PMID 26215852, 2015). "In HCC, high c-MET expression has also been found to be a poor prognostic marker, correlating with poorly differentiated tumours and lower survival rates." (PMID 28943627, 2015). "The activated MET signaling pathway not only promotes tumor cells proliferation, but also facilitates cell migration and invasion, which contributes to tumor metastasis." (PMID 26528757, 2015). "MET positivity by IHC changed in up to 40% of cases among different tumor areas, and MET amplification in 25–50%." (PMID 26041880, 2015). "We further generated patient derived tumor cell lines and screened them for the presence of METex14del and investigated the consequence of MET inhibition in these METex14del+ cells lines." (PMID 26375439, 2015). "PDC cell lines were generated from his malignant ascites and investigated for anti-tumor activity by MET inhibitors (below)." (PMID 26375439, 2015). "Cabozantinib (CBZ) is targeted against multiple receptor tyrosine kinases involved in tumour pathobiology, including hepatocyte growth factor receptor (MET) and vascular endothelial growth factor receptor 2 (VEGFR-2)." (PMID 26279137, 2015). "Significant statistical correlation was identified between c-MET protein overexpression and tumour recurrence." (PMID 26459369, 2015). "Studies have identified MET as a mediator of tumor invasion and resistance following angiogenesis inhibition." (PMID 25294187, 2015). "Among these signaling molecules, Hepatocyte Growth Factor (HGF) is released by many cell types of the tumor microenvironment to target its receptor c-MET within the cells of the primary tumor." (PMID 28536400, 2015). "Two somatic activating MET mutations have been identified in HNSCC (Y1248C, and Y1253D), which increase the kinase activity of MET and subsequently lead to tumor proliferation and metastasis." (PMID 26319934, 2015). "MET positivity by immunohistochemistry (IHC) was defined as an above-median H-score and by +2/+3 staining intensity in >50% of tumor cells (Metmab criteria)." (PMID 26041880, 2015). "Regardless, the investigators uncovered a potential flaw in MET targeting therapy in cancer, where the effects of MET kinase inhibitors, usually used to block tumor growth, are dampened by the inhibition of anti-tumoral neutrophils expressing Met." (PMID 26438048, 2015). "Overexpression of wild type MET (MET-WT) as well as expression of MET-T1010I increases colony formation, cell migration and invasion in-vitro and tumor growth in-vivo." (PMID 25605252, 2015). "We also suggest to include Batf2 as therapeutic target against cancer as Batf2 has been shown as a novel tumor suppresser gene, inhibiting growth of cancer cells through repression of hepatocyte growth factor receptor / MET signaling." (PMID 26376615, 2015). "Our prior studies have shown that MET inhibitors can effectively impair HGF-autocrine GBM tumor growth." (PMID 26381735, 2015). "Tivantinib is being currently evaluated in the clinic as a specific MET inhibitor in different tumor types." (PMID 26458953, 2015). "Her archival tumor tissue was amplified for MET by FISH in less than 2 % of nuclei, though the clinical significance of this is unclear." (PMID 26123926, 2015). "c-MET inhibitors are considered a promising therapeutic option for tumours exhibiting c-MET-status alterations." (PMID 26259250, 2015).